TIA1 (TIA1 cytotoxic granule associated RNA binding protein)
Diseases named in the same sentence as TIA1 in open-access papers (continued):
Sharing a sentence is not in itself a finding about the gene and the disease.
infection (continued). "We performed IF analysis to assess SG formation during CVB3–2Amut infection, staining for the conventional stress granule markers G3BP2 and eIF3, as well as TIA-1 and Sam68." (PMID 40875754, 2025). "Further, at late stages of infection in PRV-infected PK15 and Vero cells, G3BP1, TIA1, and IE180 localized in subnuclear regions that are devoid of marginalized host chromatin, which typically corresponds with viral DNA replication compartments." (PMID 40145738, 2025). "This seems to be true for some positive-sense single-stranded viruses as well: during infection with tick-borne encephalitis virus (TBEV), a flavivirus, TIA-1 is recruited to virus replication sites where it directly binds viral RNA." (PMID 37606964, 2023). "Infection with EV-D68 caused HuR, TiA1, and G3BP1 to colocalize, resulting in the formation of a typical SG dependent on protein kinase R (PKR) and eIF2 phosphorylation, implying that TiA1, HuR, and G3BP1 could target EV-D68's 3' untranslated region (UTR), inhibiting viral replication." (PMID 34743709, 2021). "Yet, atypical SGs in which TIA-1, TIAR, Sam68, and viral RNA are persistently aggregated in an eIF2α independent and cycloheximide-resistant manner remain during infection." (PMID 31681621, 2019). "Consistently, infection with a non-G3BP-1 binding SFV promotes a persistent accumulation of SGs containing G3BP-1 and TIA-1, which correlates with an attenuation in viral infection." (PMID 31681621, 2019). "In contrast, SG formed after infection with SINV wild type strain AR339 condensed into a single, large perinuclear granule, which also localised with host RNA binding proteins YBX1 and TIA1." (PMID 31905741, 2019). "As infection proceeded, IF revealed EV71 in 90% of the cells at 4 hpi and 95% of the cells at 6 hpi, TIA-1 and Sam68 assembled into foci and colocalized with each other in infected cells." (PMID 29415027, 2018). "In this report, we show that during infection, RABV promotes the formation of cytoplasmic SGs that contain TIA-1, G3BP1 and PABP." (PMID 27749929, 2016). "Similarly, during infection of the recombinant SINV mCherry.capsid, the virus capsid redistributed with YBX1 and TIA1 and also with VCP and G3BP1 into a single perinuclear granule." (PMID 31905741, 2019). "To determine whether HPIV3 infection induces SG formation, we infected HeLa cells with HPIV3 for up to 36 hour (h) and analyzed the distribution of SG marker proteins TIA-1 and G3BP at different time points post-infection (pi)." (PMID 29518158, 2018). "In PRRSV-infected cells, cytoplasmic granules containing SG marker proteins TIA1 or G3BP1 were not seen at 6 h post-infection (hpi) (data not shown), but they began to occur at 12 hpi and still existed at 48 hpi." (PMID 28421170, 2017). "In this study, we found that infection of PRRSV strain WUH3 (genotype 2 PRRSV) induced stable formation of robust SGs in MARC-145 cells, as demonstrated by the recruitment of marker proteins of SGs, including TIA1, G3BP1, and eIF3η." (PMID 28421170, 2017). "Both Sam68 and TIA-1 display diffuse nuclear fluorescence in mock infected and at 1 h post infection (hpi) with FMDV (data not shown)." (PMID 26695943, 2015). "We found that transfection of poly I:C (a dsRNA mimic) or infection with the R296T mutant induced the formation of G3BP1-positive/TIA1-negative RNase L-dependent bodies (RLBs) in WT cells and PKR KO cells, whereas infection with the K287T mutant induced RLBs in PKR KO cells." (PMID 34237110, 2021). "To confirm that the foci to which ZAP localizes in the context of infection are indeed SGs, we utilized a cell line overexpressing GFP-tagged hZAP and ectopically expressed RFP-tagged DCP1, a P-body cellular marker, and used indirect immunofluorescence to localize the SG marker TIA-1." (PMID 31116799, 2019).
infection (continued). "Furthermore, we demonstrated that SGs are actively disassembled at late times during infection where G3BP1, TIA1 and HuR dissociate from SGs back into the cytoplasm, while poly-A granules persist, suggesting that G3BP1-SGs are specifically targeted while other RNA granules such as P-bodies are not." (PMID 24260247, 2013). "In line with the triggering of IFN response during productive infection, the majority of the aggregates colocalized with activated RIG-I, while they were mostly negative for TIA-1." (PMID 31710640, 2019). "We similarly observed an increase in Ataxin-2 abundance and no change in HuR, TIA-1, and TIAR levels following infections with the Ugandan and Puerto Rican strains." (PMID 30944179, 2019). "During HSV-1 infection, the SG components TIA-1, TIAR and TTP are upregulated, but do not form SG, however, infection with vhs-defective HSV-1 triggers SG assembly, relying on PKR activity in the absence of vhs." (PMID 27367717, 2016). "TIA-1 is not sequestered in DNA factories; however, infection with a VV mutant lacking E3L, which activates PKR, induces aggregates that contain TIA-1, eIF3b, G3BP1 and USP10, called antiviral granules (AVGs), given that they restrict viral replication." (PMID 27367717, 2016). "Correspondingly, EV71-2AC110S infection failed to induce aSG formation; instead, EV71-2AC110S induced the formation of tSGs containing G3BP and TIA-1 in about 65% of infected cells, which could be completely dispersed by CHX." (PMID 29415027, 2018).
neurodegenerative disease (15 papers, 2017 to 2026). A disorder of the central nervous system characterized by gradual and progressive loss of neural tissue and neurologic function. "These works further underscore the pathogenic role of TIA1 aggregates in neurodegenerative diseases." (PMID 41188647, 2025). "While this review is primarily focused on four specific proteins, these trends can be observed in other IDPs associated with neurodegenerative diseases such as TIA-1, hnRNP, FUS, ataxin, and SOD1." (PMID 36834792, 2023). "A T cell-restricted intracellular antigen-1 (TIA1) protein was described as a molecular marker of degenerative disease, and the mutations related in its low complexity domain are signatures of disease." (PMID 34884901, 2021). "Mutations in various RNA binding proteins such as hnRNP A1, hnRNP A2/B1, FET protein family (FUS, TAF-15, EWSR1) Matrin-3, TIA-1 and Ataxin-244 are implicated in various neurodegenerative diseases." (PMID 29070802, 2017). "In this study, we reveal that ANXA7 enhances a dynein-driven RNP transport mechanism related with the degradation of these RNPs, thereby counteracting TIA1 aggregation in axons and providing a potential strategy to target and eliminate pathogenic aggregates underlying neurodegenerative diseases." (PMID 41188647, 2025). "Here, we characterize the molecularmechanism underlying the rigidification of liquid droplets for thelow complexity domain of the Cytotoxic granule associated RNA bindingprotein TIA1 (TIA1) stress granule protein and the influence of adisease mutation linked to neurodegenerative diseases." (PMID 36638831, 2023). "Furthermore, mutations in TIA-1 PrLD that are associated with neurodegenerative disease and multisystem proteinopathy have been shown to increase the aggregation potential of TIA-1 in vitro and delayed SG disassembly in vivo." (PMID 33621982, 2021). "CONCLUSIONS: Plasma TIA-1 is a promising biomarker candidate for neurodegenerative diseases, with alterations that reflect disease presence and severity." (PMID 41877170, 2026). "METHODS: Accordingly, in this pilot study, we evaluated the plasma TIA-1 levels in healthy controls and across spectrum of neurodegenerative diseases to assess its clinical and biological significance." (PMID 41877170, 2026). "Pathological investigations across various neurodegenerative diseases have further illuminated TIA-1's role in protein aggregation." (PMID 41446360, 2025). "Our study uncovers a direct dynein-dependent mechanism driving the retrograde trafficking of TIA1-RNPs in axons, which counteracts the pathological aggregation and axonopathies, offering potential avenues for neurodegenerative diseases." (PMID 41188647, 2025). "Mutations in RBPs that affect SG biology, including FUS, TDP-43, hnRNPA1, hnRNPA2B1, and TIA1, underlie ALS, IBM, and other neurodegenerative diseases." (PMID 34291734, 2021). "This suggests that boosting ANXA7 levels could represent a potentially effective therapeutic strategy for treating TIA1 aggregation-related neurodegenerative diseases." (PMID 41188647, 2025). "In the past few years, several different RBPs have been identified demonstrating their altered functions and aggregation properties in neurodegenerative diseases, among which TDP-43, FUS and TIA-1 are extensively studied." (PMID 30367664, 2018). "Notably, plasma TIA-1 mirrored the discriminatory patterns of CSF t-Tau and p-Tau, distinguishing non-AD neurodegenerative diseases from specifically rpAD subtype, indicating that plasma TIA-1 captures the same underlying pathophysiological processes as the “gold standard” CSF markers." (PMID 41877170, 2026).
myopathy (7 papers, 2018 to 2023). A disease of the muscle in which the muscle fibers do not function properly. "To date, a single TIA1 mutation (p.Glu384Lys) is known to cause a late-onset myopathy with rimmed vacuoles (MRVs)." (PMID 29599744, 2018). "Such difference, however, could be due to the fact that 5 of the 6 patients in the non‐VCP MSP group had the SQSTM1+TIA1 mutations associated with late‐onset myopathy and therefore skewing the results." (PMID 36861178, 2023). "The findings indicate that all the affected individuals have a myopathy associated with both variants in SQSTM1 and TIA1, respectively, suggesting that the two variants determine the phenotype and likely functionally interact." (PMID 29599744, 2018). "The lack of functional studies is certainly a limiting feature of the study, and further investigations will be needed to prove the digenic nature of the myopathy and the deleterious effects of the combined SQSTM1 and TIA1 variants in myopathy." (PMID 29599744, 2018). "These three genes have not been associated with PDB; isolated TIA1 mutations (without co‐existing pathogenic SQSTM1 variant) have not been reported as causative of both myopathy and ALS/FTD within the same pedigree." (PMID 36861178, 2023). "Distal myopathy occurred in 10 patients (5 TIA1, 2 SQSTM1 + TIA1, 1 MATR3, 1 HNRNPA1, 1VCP)." (PMID 36861178, 2023). "The combination of TIA1 and SQSTM1 variants tend to result in myofibrillar myopathy." (PMID 36998782, 2023). "Although the causality of the coexisting SQSTM1 and TIA1 variants in myopathy has not been proven, our affected individuals from three unrelated family provide further support to the digenic nature of this myopathy." (PMID 29599744, 2018). "Herein, we describe the clinical and pathological phenotype of three unrelated probands harboring the combined heterozygous TIA1 and SQSTM1 variants in the setting of MRV or myofibrillar pathology, providing evidence that co-occurrence of these variants are associated with late-onset myopathy." (PMID 29599744, 2018). "However, molecular and functional studies to dissect the likely interaction between TIA1 and SQSTM1 would shed light on the pathomechanism of the myopathy." (PMID 29599744, 2018).
neurological diseases (5 papers, 2017 to 2025). "The dysfunction of stress granules (SGs) plays a crucial role in the pathogenesis of various neurological disorders, with T cell intracellular antigen 1 (TIA1) being a key component of SGs." (PMID 39804990, 2025). "Only three of our seven probands (43%) had a family history of neurological disease, which is significantly less than for C9orf72 and SOD1 mutations and suggests that TIA1 mutations may be variably penetrant." (PMID 29216908, 2017).
genetic diseases (1 paper, 2017). "The novel C+/+/Tia1−/− model is also suited for testing the efficacy of therapeutic compounds aimed at the treatment of SMA and possibly other genetic diseases impacted by aberrant SMN and/or TIA1 expression." (PMID 28775379, 2017).
neurodevelopmental disorder (1 paper, 2021). A behavioral and cognitive disorder with onset during the developmental period that involves impaired or aberrant development of intellectual, motor, or social functions.
TIA1 also shares sentences with these, for which no sentence is quoted: vacuolar myopathy (3 papers); cognitive decline (2); diffuse large B-cell lymphoma (2); glioma (2); NK T-cell lymphoma (2); sarcoma (2); synucleinopathies (2); adenocarcinoma (1); Amyotrophic lateral sclerosis/frontotemporal dementia (1); Aphasia (1); Autoimmunity (1); B cell lymphomas (1); celiac disease (1); cellulitis (1); Duchenne muscular dystrophy (1); fibrosis (1); follicular thyroid cancer (1); hepatoblastoma (1); hereditary inclusion-body myopathy (1); HIV-1 infection (1); lentivirus infection (1); leukemia (1); liposarcoma (1); medullary breast carcinoma (1); metabolic syndrome (1); muscle disorders (1); myofibrillar myopathy (1); optic neuritis (1); osteoarthritis (1); ovarian tumors (1).
A further 10 diseases each share a sentence with TIA1 in 1 paper.